SHH (sonic hedgehog signaling molecule)
Diseases named in the same sentence as SHH in open-access papers (continued):
Sharing a sentence is not in itself a finding about the gene and the disease.
tumor (continued). "Importantly, the GDC-0449/PEG-PCL-Dox combination inhibits BxPC-3 tumor growth synergistically, which could result from the reduced tumor density and downregulation of SHH signaling observed in tumor tissues." (PMID 29042665, 2017). "Moreover, the role of SHH in tumor development was investigated in vivo." (PMID 28708091, 2017). "Moreover, we examined the expression of SHH in GC tissues and adjacent non-tumor tissues." (PMID 27039174, 2016). "The fact that intact tumor sheets were significantly decreased by SHH inhibitors in addition to a significant reduction in tumor size was further confirmed by TUNEL staining of resected xenograft tumors: the number of TUNEL-positive cells was significantly increased by SHH inhibitors (p < 0.01)." (PMID 26716648, 2016). "Deletion of the miR-17∼92 cluster was sufficient to completely abolish tumor development, pointing to the absolute requirement for the miR-17∼92 cluster, and to the lack of compensation by the miR-106b∼25 cluster, for MB development in collaboration with constitutively activated SHH signaling." (PMID 24928431, 2014). "Moreover, the dying cell stimulated living tumor cell growth could be further enhanced by SHH signaling agonists or recombinant N-terminal fragment of Shh and inhibited by SHH signaling antagonists or knockdown by Gli1shRNA." (PMID 23762282, 2013). "According to the initial classification of tumor types with TERT mutations at frequencies over 15 % (TERT-high) vs. below this threshold (TERT-low), our report suggests distinct baseline telomerase activity of the cell of origin in each of the subgroups (Group 3 ≥ Group 4 > WNT >> SHH)." (PMID 24174164, 2013). "Reciprocally, we propose that the SHH expression, detected in human cancers and previously considered as a mechanism for activation of the canonical pathway in an autocrine or paracrine manner, actually provides a selective tumor growth advantage by blocking CDON-induced apoptosis." (PMID 23940460, 2013). "Therefore, the “Phoenix Rising” pathway with caspase-mediated tumor growth stimulation and the SHH signaling pathway may both be involved in tumor cell repopulation after radiotherapy." (PMID 23762282, 2013). "However, SHH signaling appears to be crucial during tumor progression." (PMID 23940460, 2013). "In light of these genetic interactions, a growth advantage could be conferred to tumor cells that overexpress SHH through interaction with currently unknown growth promoting targets, while at the same time abrogating OLIG1 expression concomitant to MAG down-regulation." (PMID 17388669, 2007). "These analyses revealed that AMF directly targets smoothened (SMO) to disrupt the SHh signaling pathway, thereby suppressing RB stem cell (RBSC) self-renewal and tumor progression." (PMID 42305888, 2026). "Previous research has indicated an anti-correlation between GLI activity and SHH expression in PDAC cell lines as well as a correlation between the two and EMT score and PDAC tumor subtype." (PMID 40508010, 2025). "In fact, deletion of Sonic hedgehog (SHH) in a pancreatic ductal adenocarcinoma (PDAC) model also reduced stromal content and led to increased tumour growth." (PMID 39780187, 2025). "Methylation of the promoter region of GLI1, a crucial transcription factor in the SHH pathway, is reduced by H. pylori in an m6A‐dependent manner, leading to increased GLI1 expression and enhanced tumor proliferation." (PMID 40231893, 2025). "There has been a growing interest in inhibiting the SHh pathway downstream of SMO, largely because some tumours, including PDAC, have shown activation of the Gli transcription factor independent of SMO." (PMID 41561521, 2025). "Previous literature as well as work by our group has shown that PDAC cells secrete elevated levels of Hh ligands (SHH, IHH), which are thought to confer tumor-promoting stromal features." (PMID 40508010, 2025).
tumor (continued). "Profiling MB on a transcriptomic and proteomic level has revealed intertumoral heterogeneity, resulting in tumor stratification into four major consensus molecular subgroups: wingless (WNT), sonic hedgehog (SHH), Group 3 and Group 42,3." (PMID 40681754, 2025). "These subtypes uncovered specific alterations in DNA methylation, transcription, and signaling pathways involved in tumor-stromal cross-talk, e.g., hepatocyte growth factor (HGF), IGF, and SHH." (PMID 40427098, 2025). "Ectopic expression of SHH or FGF4 activated GREM1/FGF4/SHH signaling and rescued the anti-tumor effects of GREM1 knockdown in vivo." (PMID 40849639, 2025). "Mechanistically, TM exerted anti-tumor effects via downregulating GLI2, and its downtream targets, thus inhibiting the sonic hedgehog (SHH) signaling pathway." (PMID 39881254, 2025). "The results revealed differential expression of SHH, WDR72, and EPOP between tumor and adjacent normal tissues (P < 0.05), which aligned with our expected findings." (PMID 41425595, 2025). "In situ hybridization further confirmed significant expression of SHH pathway proteins, including SMO, GLI1, GLI3, and SUFU, indicating an active role of SHH signalling in promoting tumour cell proliferation and maintenance." (PMID 39568072, 2024). "Top neoantigen targets for SHH included DDX3X, PRKAR1A, and PTCH1 which are genes commonly involved in tumor progression." (PMID 39160595, 2024). "As Hh signaling is known to activate myofibroblasts and CAFs that orchestrate the tumor microenvironment, we treated human gingival fibroblasts (HGF) with SAG, SHH, or TGF‐β as a positive control." (PMID 38976559, 2024). "Under hypoxic conditions, SHH signaling pathways and endoplasmic reticulum stress (ERS) in CCA tumor tissues or tumor cell lines are activated." (PMID 39290697, 2024). "PEBP4 impacts tumor survival rates by regulating AKT, MAPK, SHH, and other signaling pathways in human." (PMID 39194863, 2024). "In NSCLC tumor tissue microarrays and cancer network databases, we found a positive correlation between HNF1A and SHH expression." (PMID 38228910, 2024). "Tracking SHH pathway components in vivo also reveals sulforaphane’s function in SHH blockade, accompanied with reduced PDAC tumor size and inhibited EMT activities." (PMID 38455361, 2023). "Further, incorporating tumor location and hydrocephalus status into the radiomic model improved the AUCs for WNT and SHH subgroups to 0.84 and 0.83, respectively." (PMID 37685265, 2023). "For example, the elimination of sonic hedgehog (SHH) signaling eliminates the myofibroblasts within the TME, and this complete depletion renders the tumor more aggressive and metastatic." (PMID 37345148, 2023). "SHH overexpression was observed in OSCC, whereas expression of PTCH1 and GLI1/2 was noted in the vascular cells in the front of the tumor." (PMID 37626893, 2023). "In a 3-fold cross-validation scheme, the molecular subgroup prediction task, with the assistance of tumor segmentation and prognosis tasks, achieved AUCs of 0.96, 0.96, 0.99, and 0.96 for WNT, SHH, Group 3, and Group 4 subgroups, respectively." (PMID 37685265, 2023). "Since more than a quarter of MB patients show activation of the SHH signaling pathway shown by GLI2/1 immunopositivity, activated forms of GLI2 preserve pathway activity and support survival of the tumor cells, indicating GLI2 activity as a key driver for MB." (PMID 37608807, 2023). "Acute treatment (3 days in vivo) in both subtypes resulted in significant reductions in the levels of SHH pathway genes, indicating that on-target, therapeutic dosing of LDE225 was achieved in both tumor subtypes." (PMID 36688010, 2022). "As a downstream target of SHH signaling, the expression of CDK6 is elevated in human MBs and its pharmacological inhibition by palbociclib resulted in attenuated tumor growth and prolonged survival in an MBSHH mouse model." (PMID 35573667, 2022).
tumor (continued). "The findings that inhibition of SHH signaling reduces ECM deposition and αSMA-positive cells suggests that tumor suppressive CAFs are involved among αSMA-positive CAFs." (PMID 36010986, 2022). "NF-κB(p65), SHh and GLI1 were expressed in all tissues analyzed, showing higher NF-κB(p65) and GLI1 expression levels in tumor vs. normal samples." (PMID 35805202, 2022). "In the context of PDA, HH ligands (primarily sonic hedgehog [SHH] and indian hedgehog [IHH]) are secreted by tumor cells and bind to the canonical receptor patched 1 (PTCH1) on fibroblasts." (PMID 35867772, 2022). "Corroborating these findings, SHH mRNA was highly expressed in 96% of non-muscle invasive bladder cancers but decreased to 51% of the more aggressive muscle invasive bladder cancers suggesting the loss of Hh pathway activity with increasing tumor aggressiveness." (PMID 36010600, 2022). "Four main signaling pathways are involved in SOX2 expression favoring tumor maintenance: TGF-β, SHH pathway, EGFRvIII, RhoA-dependent pathway and focal adhesion kinase (FAK) signaling." (PMID 36232992, 2022). "Using IHC, we confirmed the presence of SHH in both stromal and cancer cells of EAC, while BMP2 and 4 were mostly expressed in the cytoplasm of the tumor cells." (PMID 35902550, 2022). "We demonstrate a relevant role of WNT and SHH signaling in IO-MEPL and report the first mouse model to generate tumor-like lesions with features of IO-MEPL." (PMID 34785636, 2021). "This has been investigated for WNT and SHH MB, with WNT tumours thought to arise from the extracerebellar lower rhombic lip, and SHH from cerebellar granule cell precursors (GCPs)." (PMID 34195095, 2021). "To identify the gene fusions within MB subgroups, we used the Arriba algorithm to identify approximately 149 gene fusion events from 52 tumor samples including six WNT-MBs, 16 SHH-MB, 14 G3-MB, and 16 G4-MB in the Asian MB cohort." (PMID 33681213, 2021). "However, cilia may play tumor suppressive or oncogenic roles depending on SHH pathway regulation." (PMID 33906647, 2021). "A similar pattern is also seen with SHH inhibitors, as one study has shown that treating EGFR inhibitor-resistant HNSCC cells with the SHH inhibitor IPI-926 reduces tumor growth and blocks tumor recurrence in patient-derived HNSCC xenografts." (PMID 35048028, 2021). "In an autocrine manner, SHH proteins secreted by TEM cells, including astrocytes, activate signaling in the surrounding stroma, which provides a favorable microenvironment for tumor growth." (PMID 34436033, 2021). "Targeting the Sonic hedgehog (SHH)–Smoothened (SMO) signaling axis increases cancer cell proliferation, owing to inhibition of the tumor-restraining phenotypes of myCAF by SHH-SMO." (PMID 35008832, 2021). "In GSCs, specific disruption of the SHH/GLI1 axis dictates the chemoresistant and radioresistant properties of the tumor and ultimately disease prognosis." (PMID 34012965, 2021). "To study the possible mechanism of inhibition of SHH-induced MB by LOF of KIF20A, we looked at cell cycle exit and re-entry in tumor-initiating GNPs of the Ptc single- and Ptc/Kif20a double-knockout mice." (PMID 33976373, 2021). "The interaction between SHH and PTHC1 plays an important role during tumor growth and the regulation of apoptosis." (PMID 34073664, 2021). "It is shown that SHH promotes macrophage M2 polarization and reduces effector CD8+ T-cell recruitment to the tumor." (PMID 34831357, 2021). "Although once regarded as a single tumour entity, it is now widely accepted that there are four distinct molecular subgroups of medulloblastoma (WNT, SHH, Group 3, and Group 4), which differ in their patient demographics, metastatic potential, and prognosis." (PMID 33608621, 2021). "Similarly, targeting SHH might lead to augmented tumor progression." (PMID 34503252, 2021). "A xenograft assay validates the tumor growth-impeding effect and inhibition of CXCR4/SHH/GLI1 signaling cascade after ETV4 depletion." (PMID 34052833, 2021).
tumor (continued). "Among the top pathways, including 31 activated in at least four tumor types, we observed a strong impact of CTNNB1 as well as several other pathways described in the literature as influencing anti-tumor immunity such as MYC, PPARG and SHH (sonic hedgehog)." (PMID 33106165, 2020). "Nonetheless, several SHH inhibitors are already FDA-approved (e.g., vismodegib, sonidegib, and glasdegib) in the context of some SHH-driven tumor types." (PMID 32722427, 2020). "A SHH inhibitor, IPI-926, led to reduced tumor growth and metastasis, increased vascular density and intratumoral GEM concentration in orthotopic mouse models of PDAC." (PMID 33520728, 2020). "CD24-/CD15+ expression was predominantly found on WNT tumours, while CD24+/CD15- expression was correlated with SHH, Group 3 or Group 4 designation." (PMID 30657775, 2019). "In the case of oncogenic miRNAs, the miR-17-92 cluster was induced by SHH signaling and MYCN and promoted tumor development in vitro and in vivo." (PMID 31763623, 2019). "This paracrine mechanism is characterized by binding of tumor-secreted Hh ligands (SHH, Indian Hedgehog (IHH), or Desert Hedgehog (DHH)) to PTCH1 receptors, and elevated levels of GLI1, GLI2, PTCH1, and SMO genes in the tumor-adjacent stroma." (PMID 31658643, 2019). "The proliferation of the patient tumor cells (225ZL) was inhibited by arsenic trioxide (ATO), which is an inhibitor of the SHH pathway, by linsitinib, which is an inhibitor of IGF1R and INSR, and by ceritinib." (PMID 31480400, 2019). "SHH and DHH overexpression was positively correlated with Ki-67 index, tumor stage and grade, lymph node involvement, metastasis, recurrence, and BC-specific death." (PMID 31027259, 2019). "Over-expression of SHH, DHH and GLI1 was significantly correlated with advanced stages and tumour grades of the cohort." (PMID 29329585, 2018). "SHH, DHH, PTCH1 and GLI1 were significantly over-expressed in tumours as compared with respective normal mammary tissues." (PMID 29329585, 2018). "We still need to have a better understanding of how osthol regulates specific signaling pathways, such as VEGF/VEGFR, PDGF/PDGFR and SHH/GLI pathways, and exert differential modulation of oncogenic and tumor suppressor microRNAs." (PMID 29301373, 2018). "IHC staining was undertaken to evaluate the expression of Hh pathway components (SHH, PTCH1 and GLI1) in the primary tumour and their respective adjacent histologically normal epithelium." (PMID 30379908, 2018). "A major strength of our study is that we compared the levels of individual Hh pathway components (SHH, PTCH1, and GLI1) in primary tumours with tumour adjacent normal epithelium." (PMID 30379908, 2018). "In models 6 and 8, SHH and IHH were between 1.6- and 6.2-fold up-regulated in human tumour epithelium at one to three weeks following irradiation (p<0.05)." (PMID 29715275, 2018). "Here, suppression of SHH signaling in fibroblasts (GAS1−/−, BOC−/−) increased angiogenesis through upregulation of fibroblast-derived angiopoietin-1 and 2 and augmented tumor growth." (PMID 30108679, 2018). "A significant correlation of SHH, DHH and GLI1 expression with advanced tumour size, stages, grades, nodal involvement and distant metastasis was observed (p < 0.05)." (PMID 29329585, 2018). "PTCH1, SHH, DHH, and GLI1 over-expression were observed in 74%, 95%, 92% and 98% tumour specimens of the cohort." (PMID 29329585, 2018). "Mean mRNA values of SHH, DHH and GLI1 showed gradual increase with tumour size, nodal spread and distant metastasis." (PMID 29329585, 2018). "Significant correlation was observed between SHH (R.E = 12.76 ± 5.12, p < 0.0001), DHH (R.E = 9.8 ± 5.1, p < 0.05) and GLI1 (R.E = 12.3 ± 3.9, p < 0.0001) and invasive tumour size." (PMID 29329585, 2018). "As the key regulators of Hedgehog pathway, SHH, SMO and GLI1 are upregulated in NSCLC tumor tissues compared to normal tissues." (PMID 28507311, 2017).
tumor (continued). "Patched was decreased in 2/3 of the tumor samples, while Gli1 was decreased in all 3 sample s, indicating GDC-0449 downregulated the SHH signaling in vivo." (PMID 29042665, 2017). "TGFβ, SHH, and wingless-type MMTV integration site family (Wnt) also crosstalk to regulate mesenchymal transition (EMT) in tumor progression." (PMID 28708091, 2017). "Throughout the tumor collection a strong and significant correlation of GLI1 and SHH expression was observed (Spearman r-coefficient 0.8062; p = 0.0065)." (PMID 27109116, 2016). "Reciprocal colony growth is dependent on SHH activation of PSCs and IGF1R/AXL-AKT activity in tumor cells." (PMID 27087446, 2016). "MB belongs to the embryonic tumor family and recent genomic studies have led to a novel classification into four molecular subgroups (i.e. WNT; Sonic Hedgehog Homolog, SHH; Group 3 and Group 4)." (PMID 27174915, 2016). "Additional work will be necessary to determine if this relates to currently undefined differences in SHH and IHH signaling or alternate pathways promoting tumor cell IHH secretion." (PMID 26755648, 2016). "Some studies also observed CYR61 activates the Wnt/Catenin, the Sonic Hedgehog (SHh), the MMP, the MAP kinase, the NF-κB and COX2 signaling pathways in tumor cells." (PMID 27105510, 2016). "Correlation analysis revealed that the SHH and GLI1 expression levels significantly correlate on transcript level throughout the tumor collection (Spearman r-coefficient 0.8571; p = 0.0238)." (PMID 27109116, 2016). "Co-activation of both SHH and CXCR4 resulted in higher expression of cyclin D1, while CXCR4 antagonism, resulted in decreased cyclin D1 expression and also blocked maximal MB tumor growth." (PMID 26512695, 2015). "The expression of SHH pathway proteins is suppressed in tumours of MNA patients, suggesting that inhibition of SHH signalling contributes to MYCN initiated transformation." (PMID 26673823, 2015). "SHH and increased EGFR expression are known to synergize and promote diverse events, including neural stem cell proliferation as well as tumor initiation and progression." (PMID 26158413, 2015). "Although alterations in SHH pathway genes (e.g.PTCH1, SUFU) are observed in many of these tumours,high throughput genomic analyses have identified few other recurringmutations." (PMID 24252690, 2013). "In support of this notion, we present the preclinical demonstration that interference with the SHH–CDON interaction triggers a CDON-dependent apoptosis in vitro and tumor growth inhibition in vivo." (PMID 23940460, 2013). "The SHH overexpression was observed in 96.0% of NMIBC and 52.4% of MIBC, and the median SHH mRNA level decreased gradually from pTa low-grade tumours (121.9) to ⩾pT2 tumours (3.92)." (PMID 22361633, 2012). "Using the hair follicle as internal control (set at 100% positivity), the expression of SHH, APC and RASSF1A in tumor cells was significantly lower (all p-values <0.001)." (PMID 23284750, 2012). "Due to the many similarities between the role of the SHH, Notch, and Wnt pathways and TSC in tumor development, maintenance, and progression, recent research has begun to focus on the intimate relationship of embryonic signaling pathways and TSC." (PMID 21394230, 2011). "We found that the SHH signalling pathway is reactivated in human CRCC and that it converges to various oncogenic pathways to orchestrate tumor growth." (PMID 20015350, 2009). "Our study found that SH downregulated the protein and mRNA expression of SHh, PTC, SMO, Gli1, and Gli2 in the Hedgehog pathway, suggesting that SH might inhibit tumor progression via suppressing the Hedgehog pathway activation." (PMID 41444284, 2025). "In this scenario, it has been demonstrated that genistein, by acting on specific signaling pathways (i.e., Sonic Hedgehog (SHH), Wnt/β-catenin, Notch, NF-κB JAK-STAT, PI3K/Akt/mTOR signaling), affects CSC proliferation, thereby inhibiting tumor invasiveness and metastasis." (PMID 39940882, 2025).